DTX1 (deltex E3 ubiquitin ligase 1)
Diseases named in the same sentence as DTX1 in open-access papers (continued):
Sharing a sentence is not in itself a finding about the gene and the disease.
COVID-19 (1 paper, 2021). A disease caused by infection with severe acute respiratory syndrome coronavirus 2. "In summary, our search for target genes in the severe COVID-19-risk loci in chromosome 12 revealed three putative causal eGenes that display prominent cell-type-restricted effects—OAS1 in NCM, OAS3 in T-cell subsets, and DTX1 in B cells." (PMID 34799557, 2021).
gastric adenocarcinoma (1 paper, 2018). "We found that overexpression of DTX1 in human gastric adenocarcinoma AGS cells decreased the levels of c-FLIPL and c-FLIPS." (PMID 29374180, 2018). "We found that expression of the ubiquitin E3 ligase DELTEX1 (DTX1) is reduced in gastric adenocarcinoma tissues from patients." (PMID 29374180, 2018).
glomerulonephritis (1 paper, 2023). A renal disorder characterized by damage in the glomeruli. "Dtx1 is an important signaling transcriptional regulator downstream of the Notch receptor, and it was reported that Notch inhibition leads to the amelioration of glomerulonephritis in a murine model of systemic lupus erythematosus by inhibiting the inflammation response." (PMID 38132237, 2023).
head and neck squamous cell carcinoma (1 paper, 2019). A squamous cell carcinoma that arises from any of the following anatomic sites: lip and oral cavity, nasal cavity, paranasal sinuses, pharynx, larynx, and salivary glands. "Notch-regulating DTX1, found here to be underexpressed in males compared to females, has been identified as a putative tumor suppressor gene in head and neck squamous cell carcinoma." (PMID 31615477, 2019).
liver cancer (1 paper, 2011). An epithelial or non-epithelial malignant neoplasm that arises from the liver. "In our study, the result of stem cell microarrays showed that DTX1 and Ep300 were highly expressed in liver cancer stem-like cells." (PMID 21669008, 2011).
malignant glioma (1 paper, 2013). A grade III or grade IV glioma arising from the central nervous system. "In conclusion, we propose the alternative Notch pathway via DTX1 as an oncogenic factor in malignant glioma." (PMID 23451269, 2013).
melanoma (1 paper, 2022). A malignant, usually aggressive tumor composed of atypical, neoplastic melanocytes. "Furthermore, DTX1 levels remained constant in Usp27x-overexpressing WM1158 melanoma cells even in the presence of pIC." (PMID 35044632, 2022).
Obesity (1 paper, 2022). Accumulation of substantial excess body fat. "For those 12 genes, six of them (DDO, SEPT9, TMEM45B, RXRα, ZNF395 and AHRR) were previously reported to be implicated in the obesity or related diseases and the rest six were novel (PACRG, LINC00494, KLHL4, DTX1, VCX3A and VSTM1)." (PMID 35568907, 2022).
poisoning (1 paper, 2024). A condition or physical state produced by the ingestion, injection, inhalation of or exposure to a deleterious agent. "The okadaic acid (OA)-group toxins, including OA, dinophysistoxin-1 (DTX1), dinophysistoxin-2 (DTX2), and dinophysistoxin-3 (DTX3), cause diarrheic shellfish poisoning in humans." (PMID 38147248, 2024).
psoriasis (1 paper, 2018). An autoimmune condition characterized by red, well-delineated plaques with silvery scales that are usually on the extensor surfaces and scalp. "While all family members had CARD14 mutations, the PRP sufferers had an additional frame-shift mutation in DTX1, a regulator of regulatory T cells, while the psoriasis-affected individual harbored a mutation in NLRC5, a molecule that activates NF-κB but also regulates MHC-I transcription." (PMID 30386326, 2018).
small cell lung carcinoma (1 paper, 2021). Small cell lung cancer (SCLC) is a highly aggressive malignant neoplasm, accounting for 10-15% of lung cancer cases, characterized byrapid growth, and early metastasis. "In contrast, patients with small cell lung cancer (SCLC) carrying DTX1 mutations showed a worse response to chemotherapy and a lower OS rate, suggesting that mutations in the same gene may play opposite roles in different subtypes of malignant tumors in the same organ." (PMID 34513839, 2021).
thymoma (1 paper, 2015). A neoplasm arising from the epithelial cells of the thymus. "The converse regulatory mechanism between the thymoma cell line and developing nervous system suggested that the regulation of Dtx1/dtx1 expression by Notch signaling is highly dependent on the cell type." (PMID 26714454, 2015). "A previous study showed that the constitutively active form of Notch upregulated Dtx1 expression in a mouse thymoma cell line." (PMID 26714454, 2015).
tumor (21 papers, 2010 to 2025). "The most frequently mutated genes in the tumor tissue cohort were DTX1 (37%), CD79B (35%), BTG1 (30%), BTG2 (30%), and TMSB4X (30%)." (PMID 36280874, 2022). "In this case DTX1 appears to act as a tumour suppressor and downregulation of DTX1 is therefore associated with poorer prognosis." (PMID 35204725, 2022). "Next-generation sequencing revealed six tumor-specific mutated genes (IGH/BCL6, TNFAIP3, PRDM1, CREBBP, DTX1, and FOXO1)." (PMID 37884941, 2023). "The test results showed that the tumor-specific mutations in this sample were as follows: BCL6, TNFAIP3, PRDM1, CREBBP, DTX1, and FOXO1." (PMID 37884941, 2023). "The effect of SAM to decrease methylation was proved to be beneficial in certain genes (HT-29: DTX1, GATA4, SEZ6L, TP53INP1; SW480: HAAO, TAL1), whose hypermethylation was associated with tumor progression according to the scientific literature." (PMID 32784836, 2020). "Several of the remaining 21 genes not in the GS, such as MYH14, MED23, and ZFP36L1 in BRCA, and ZNF292, FUBP1, and DTX1 in CLL, had also been implicated in tumor development." (PMID 29030609, 2017). "Microarray gene expression analysis further identified a DTX1-specific, MAML1-independent transcriptional program - including microRNA-21- which is functionally linked to the changes in tumor cell aggressiveness." (PMID 23451269, 2013). "To determine how these changes in MAPK and PI3K/PKB signaling affect proliferation, we performed BrdU incorporation assays to detect alterations in tumor cell proliferation in relation to DTX1 levels." (PMID 23451269, 2013). "Altogether, DTX1 activates a set of transcripts with oncogenic functions and down regulates tumor suppressors in parallel." (PMID 23451269, 2013). "In vivo studies indicate that chronic exposure to OA may promote tumor, and both OA and DTX1 showed a tumor promoting activity in a two-stage carcinogenicity study in mice." (PMID 30096904, 2018). "Moreover, employment of TCGA's control population with matched clinical characteristics confirmed our original discovery of hypermethylation and downregulation of candidate genes, especially the leading candidate, DTX1, in tumor samples." (PMID 28146432, 2017). "Interestingly, separation of HNSCC samples by DTX1 expression separated the tumor samples into two subsets of samples, with different expression of NOTCH pathway genes in each group." (PMID 28146432, 2017). "Given the ability of HIF-1α protein to degrade Foxp3 (refs 32, 33), we propose that DTX1 may also contribute to the stability of tumour-infiltrated Tregs by antagonizing HIF-1α." (PMID 25695215, 2015). "All tumor biopsies and all ex vivo cells showed robust DTX1 expression at the transcript level." (PMID 23451269, 2013). "DTX1, as a member of DTX proteins, has been already reported to influence the progression of tumor cells, which indicated that DTX family proteins played critical roles in tumor cells." (PMID 33403043, 2021). "Since DTX1 was downregulated in HNSCC tumor samples, it is expected to have tumor-suppressor properties." (PMID 28146432, 2017). "However, DTX1 showed almost no methylation in normal tissues, resulting in high tumor specificity." (PMID 28146432, 2017).
cancer (12 papers, 2010 to 2025). A tumor composed of atypical neoplastic, often pleomorphic cells that invade other tissues. "The level of APH1A, CTBP1, HEY1, HEY2, JAG2, NOTCH4 was significantly higher in cancer samples compared to the control group, while the concentration of DTX1 TLE2, TLE4 was below the detection threshold." (PMID 41463075, 2025). "Among the eRNA–hub gene interaction pairs, 3 eRNAs related to URGs were subsequently selected, and DTX1 had the greatest degree of connection; it was targeted by two eRNAs (PTGDS, TP73-AS1), indicating an association with human cancer that is increasing." (PMID 36681855, 2023). "A likely cause for the downregulation of c-FLIPS in these cancer cells is that c-FLIPL is hetero-dimerized with c-FLIPS in vivo and that the binding of DTX1 to c-FLIPL induces the degradation of c-FLIPL-c-FLIPS dimers." (PMID 29374180, 2018). "DTX1 has been shown to enhance the aggressiveness and survival of cancer cells through the activation of the RTK/PI3K/AKT and the MAPK/ERK mitotic pathways and induction of anti-apoptotic MCL1." (PMID 26654227, 2015). "Cells were seeded in serum-free neurobasal medium to check for differences in floating cancer sphere formation as an additional measure for the oncogenic effect of DTX1." (PMID 23451269, 2013). "We provide molecular insight in how a modulation of DTX1 levels changes the signaling networks in cancer cells and relate these findings to changes in the proliferative, migratory and clonogenic potential." (PMID 23451269, 2013). "DTX1 also plays a pivotal role in tumorigenesis, invasion, and metastasis of several cancers." (PMID 34513839, 2021). "Our results suggest that induction of DTX1 could be a new approach to enhancing the benefits of TRAIL-mediated cancer therapy." (PMID 29374180, 2018). "We next examined whether the DTX1-mediated downregulation of c-FLIP contributes to sensitization of cancer cells to TRAIL-induced cell death." (PMID 29374180, 2018). "Differential expression and methylation of 3 selected candidates (BANK1, BIN2, and DTX1) were confirmed in an independent HNSCC cohorts from Johns Hopkins and TCGA (The Cancer Genome Atlas)." (PMID 28146432, 2017). "Notch1 signaling is increased in a variety of cancers and activates downstream target genes, including HES1, HES5, DTX1, NRARP, and c-MYC." (PMID 20161710, 2010). "Most likely, DTX1 expression per se may not be sufficient to either drive or suppress cancer progression, and additional studies are needed to clarify its contextual role in cancer." (PMID 37443713, 2023). "However, DTX1 also controls genes which are not regulated by the canonical Notch pathway and have a direct impact on cancer progression, e.g. miR-21 which has a well-established role as an oncomir through several modes of action." (PMID 23451269, 2013). "However, the role of DTX1, a mediator of non-canonical Notch signaling, has not been elucidated in cancer." (PMID 23451269, 2013). "On the other hand, DTX1 can also positively regulate cell context-dependent non-canonical NOTCH1/2 signaling pathways and NOTCH1/2-independent signaling pathways in cancer." (PMID 26654227, 2015).
infection (2 papers, 2016 to 2017). The state of being infected such as from the introduction of a foreign agent such as serum, vaccine, antigenic substance or organism. "The genes that flank the Oas cluster (Dtx1 and Rph3a) were identified as expressed compared to mock-infection in our heatmap." (PMID 28592649, 2017).
DTX1 also shares sentences with these, for which no sentence is quoted: Alzheimer disease (1 paper); aortic stenosis (1); fracture (1); Hepatitis B (1); inflammatory bowel disease (1); Juvenile onset (1); marginal zone lymphoma (1); Osteoblastoma (1); splenic marginal zone lymphoma (1); systemic lupus erythematosus (1); T-cell acute lymphoblastic leukemia (1); thymic lymphoma (1); thymic tumors (1).